HIF1A (hypoxia inducible factor 1 subunit alpha)
Diseases named in the same sentence as HIF1A in open-access papers (continued):
Sharing a sentence is not in itself a finding about the gene and the disease.
ischemia (continued). "Results from the present study depicted that blocking blood flow elevates HIF-1α, lipid peroxidation, peroxynitrite level in ischemic vessels while ranolazine administration partially attenuates ischemia driven HIF-1α expression." (PMID 20479865, 2010). "However, also different findings are reported as a cardiac specific Hif-1α knockout leads to increased cardiac damage in an ischemia/reperfusion injury mouse model." (PMID 39820339, 2025). "Importantly, PCL-Gd/CA nanoparticles also decreased HIF-1α and IL-1β levels in OHCs exposed to experimental ischemia/reperfusion." (PMID 39786699, 2025). "During ischemia, HIF-1α accumulates due to reduced oxygen-dependent degradation." (PMID 40730830, 2025). "Therefore, we investigated the HIF-1α nuclear translocation after temporary ischemia induced by cardiac arrest and altered the blood flow conditions in the brain." (PMID 40141795, 2025). "Separately, research suggests it may prevent cerebral edema after ischemia by inhibiting the HIF-1α/VEGF pathway and stabilizing β-ENaC ion channels in the brain." (PMID 41451367, 2025). "Moreover, ischemia-associated significant increases in apoptotic cells in the inner retina, inflammatory biomarker MCP-1, and ischemic indicator HIF-1α were significantly nullified by catalpol." (PMID 40362263, 2025). "Moreover, we observed the enhanced expression of the HIF1α gene 7 days post-stroke in the hemisphere affected by ischemia." (PMID 40332314, 2025). "Therapies aimed at HIF-1α-regulated metabolic pathways, including glycolysis and mitochondrial activity, may shield cells from ischemia injury and encourage tissue regeneration." (PMID 39099978, 2024). "Therapies aimed at HIF-1α-regulated metabolic pathways, including glycolysis and mitochondrial activity, may shield cells from ischemia injury and promote tissue regeneration." (PMID 39099978, 2024). "The role of HIF-1α may vary depending on the degree and stage of ischemia, and a consensus on this issue has yet to be reached." (PMID 39717345, 2024). "Interestingly, since placental ischemia and hypoxia are typically found in preeclampsia, HIF1α has also been related to being involved in preeclampsia." (PMID 38276547, 2024). "In conclusion, the enterocyte changes in HIF1α immunoreactivity over time indicate that this transcription factor may play a role in the intestinal response to ischemia in horses." (PMID 36908508, 2023). "Reduced oxygen concentrations in culture have been shown to stabilize HIF-1α, thereby mediating the expression of several genes that promote angiogenesis, prevent apoptosis, and induce migration and homing of these cells to sites of ischemia." (PMID 37612731, 2023). "Such a role of these proteins in cellular reactions during ischemia raises the question of the development of new neuroprotective agents which are able to provide modulation/protection of the genes encoding the synthesis of HSP 70 and HIF-1a proteins." (PMID 37138769, 2023). "In addition, previous studies using a focal or global cerebral ischemia model have found that overexpression of HIF-1α was involved in various adaptive responses and protected the neuronal cells from ischemia- or hypoxia-induced damages in vitro or in vivo." (PMID 35449809, 2022). "This is only applied to the role of HIF-1α-mediated mitophagy at an early phase of ischemia, which may result in cardiac protection, while prolonged autophagy may activate cell death in H9C2 cardiomyoblasts and Sprague Dawley rat models." (PMID 35205167, 2022). "Interestingly, more recent studies also implicate HIF1A in mediating the cardioprotective effects of remote ischemic preconditioning, where repeated episodes of remote ischemia to a limb can produce protection from myocardial or acute kidney injury." (PMID 36247475, 2022). "However, studies indicate that while enhanced cardiac expression of HIF-1α is beneficial, protection requires activation before the onset of lethal ischemia." (PMID 36174675, 2022).
ischemia (continued). "Compared with the sham group, the expression of HIF-1α in ischemia group increased." (PMID 35586047, 2022). "A significant high HIF-1α gene expression was registered in the ischemia group and the rats treated with BM-MSCs compared with the control group, but with significant reduction in HIF-1α gene expression in the treated group compared with the ischemic non-treated group." (PMID 34630958, 2021). "HIF1A plays a vital role in kidney diseases induced by ischemia and nephrotoxicity." (PMID 34802380, 2021). "Arginine may protect against ischemic neuronal death after rat ischemia and reperfusion injury and inhibit inflammatory response by suppressing HIF-1α in OGD-cultured microglia and rat ischemic brain tissue." (PMID 34966392, 2021). "Additionally, inactivation of HIF-1α leads to increased brain damage and decreased survival following ischemia." (PMID 34395432, 2021). "Moreover, upregulation of VEGF via HIF-1α activation under hypoxia can also protect cardiomyocytes against ischemia injury and repair ischemia/reperfusion injury in lung tissue in vivo." (PMID 34368116, 2021). "DFO may prevent cognitive dysfunction secondary to ischemia via activation of the HIF-1α response, providing neuroprotection following occlusive events akin to its role following ischemic stroke." (PMID 33513737, 2021). "Most of the cortical HIF-1α staining was found in the glomerular and proximal tubular regions of the nephron, which may be attributed to contrast-mediated ischemia." (PMID 32200666, 2020). "A few in vitro studies have hypothesized this cardioprotective role during ischemia to be mediated by upregulating HIF-1α through the regulation of the PTEN/Akt pathway as well as inhibiting its proapoptotic target gene PDCD4." (PMID 33114482, 2020). "The activation of the CNS-specific promoter by HIF1A supports a role of CNS isoforms in ischemia." (PMID 31471878, 2020). "Collectively, these results show that increased transport of carnosine into skeletal muscle myoblasts may potentiate HIF-1α/VEGF-mediated angiogenesis during ischemia." (PMID 31312142, 2019). "Therefore, we propose that the contribution of HIF-1α to angiogenesis is rare in the late phase of ischemia." (PMID 28869535, 2017). "Others demonstrated that the increase of HIF-1α expression under hypoxic conditions induced apoptosis, promoted hypoxia-induced delayed neuronal death, and enhanced the brain damage induced by ischemia." (PMID 28697748, 2017). "In this study, we analyzed the role of HIF-1α-induced autophagy on multiterritory perforator flap survival in rats, and also elucidated whether HIF-1α participates in the regulation of cell death under ischemia/reperfusion injury." (PMID 28924179, 2017). "Thus, HIF-1α appears to be a potential target for the development of novel therapeutic interventions in ischemia-related neurological disease." (PMID 28106731, 2017). "Consequently, both neuroprotective and detrimental effects of HIF-1α have been observed in animal models of acute ischemia." (PMID 28106731, 2017). "CCH is a less severe form of ischemia that develops more slowly than acute ischemic stroke, therefore, HIF-1α may play a more important role in this pathological process." (PMID 28106731, 2017). "The role for HIF-1α in mediating either pro-death or pro-survival responses may depend on the severity and duration of the ischemia insult and the types of pathological stimuli." (PMID 28106731, 2017). "Upon ischemia, the HIF-1α oxygen-sensing pathway is activated which increases SDF-1α expression." (PMID 29228630, 2017).
ischemia (continued). "Our experimental results from PHD inhibition suggest that the 26S proteasomal pathway contributed to the degradation of HIF-1α in ischemia, at least in our experimental setting, indicating that PHD activity was not completed suppressed at the low oxygen conditions." (PMID 28566998, 2017). "It is worth pointing out one important fact, that is, whether HIF-1α is protective or detrimental in ischemic stroke depends on the stroke stage, ischemia severity and ischemia duration." (PMID 28979191, 2017). "These showed that ischemic postconditioning could suppress the expression of HIF-1α in neurons under ischemia condition." (PMID 26715469, 2015). "Immunofluorescence confirmed that HIF-1α was mainly located in cytoplasm of neurons, but few in astrocytes, while ischemia injury could induce HIF-1α increase." (PMID 26715469, 2015). "Post-ischemia treatment with Ast IV significantly increased HIF-1α, iNOS, and Bcl2 protein expression, to 4.36±0.20-fold, 4.11±0.14-fold, and 4.14±0.17-fold of the control, respectively, whereas Caspase3 expression decreased to 0.45±0.087-fold that of the control (vs. SIR group, P<0.01)." (PMID 25238237, 2014). "Based on our preliminary experiments, 5 μM 2-MeOE2-treated cardiomyocytes and 2 μM 2-MeOE2-treated isolated hearts were used to investigate the role of the HIF-1α pathway in mediating the protective effects of post-ischemia treatment with Ast IV against myocardial IRI." (PMID 25238237, 2014). "First, do all types of cortical neurons express HIF-1α in ischemia?" (PMID 24887017, 2014). "Ischemia takes place early in the diabetic retina and our results show that B1R antagonism may be effective in reducing HIF-1α expression and subsequent retinal ischemia." (PMID 22470485, 2012). "Interestingly, the tendency was for HIF-2α protein to be more highly expressed in the proximal parts of the flaps than in the distal parts, although the expression of HIF-1α protein was higher in the distal parts, which are more severely ischemia." (PMID 22880134, 2012). "In conclusion, we observed that post-ischemia IH intervention rescued ischemia-induced spatial learning and memory impairments, likely by inducing hippocampal neurogenesis and c-Fos expression through mediators including pMAPK and HIF-1α." (PMID 21887361, 2011). "In this sense, the HIF-1α mRNA response could to be a marker of the degree of I/R injury, i.e., the higher HIF-1α mRNA response after ischemia, the more pronounced I/R injuries." (PMID 21771288, 2011). "The present protein analyses and results strongly support the hypothesis that catalpol exerts its anti-inflammatory, antioxidative, and anti-ischemic/hypoxic properties via mechanisms of downregulating the ischemia-associated overexpression of MCP-1, β-catenin, HIF-1α, VEGF, and angiopoietin-2." (PMID 40362263, 2025). "We hypothesized that survivin and HIF-1α levels wouldincrease with ischemia." (PMID 38656026, 2024). "Moreover, ischemia-induced limb fibrosis was ameliorated by HIF-1α+/+ hMSC alone." (PMID 37158785, 2024). "Another study examined the expression of HIF-1α in the different neuronal phenotypes under in vitro and in vivo ischemia and showed that the HIF-1α expressing GAD65/67-positive interneurons also possessed high levels of glutathione, which might explain their longer survival under cerebral ischemia." (PMID 37373327, 2023). "However, it is assumed that when the blood flow is adequate to provide oxygen supply to cells, HIF-1α will undergo quick degradation, explaining the significant reduction in its gene expression with BM-MSCs treatment compared with the ischemia group in the current study." (PMID 34630958, 2021). "Therefore, unveiling the Janus face of HIF-1α and its target genes in different type of cells and exploring the role of HIF-1α in inflammatory responses after ischemia is of great importance for revealing the pathogenesis and identifying new therapeutic targets for ischemic stroke." (PMID 34966392, 2021).
ischemia (continued). "Moreover, the number of GFAP cells in white matter (WM), subventricular zone (SVZ), and striatum were decreased, implying that HIF-1α activation possesses a neuroprotective effect after ischemia by hindering astrocytes activation and pro-inflammatory cytokines." (PMID 34205911, 2021). "Also, the exact molecular mechanism by which ADPN stimulated HIF-1α in ischemia penumbra was unknown, whether the ADPN receptor or other signaling pathway took part in this needs further exploration." (PMID 34336097, 2021). "Although HIF‐1α is known to play a key role in the protection from acute ischemia, recent evidence suggested that prolonged unregulated activation of HIF‐1α could enhance maladaptive responses, which lead to glomerulosclerosis and interstitial fibrosis in multiple animal models." (PMID 30614190, 2019). "Here our data showed that blocking β2-AR significantly inhibits ischemia-induced BBB damage through suppressing HIF-1α expression and occludin degradation, indicating that β2-AR-HIF-1α signaling may represent promising therapeutic targets for preventing ischemia-induced BBB damage." (PMID 28855859, 2017). "Therefore, it is possible that HIF-1α may be induced by ischemia, resulting in increased microvascular permeability and AQP1-dependent myocardial edema." (PMID 26348407, 2015). "In the present study, the upregulation of iNOS by post-ischemia treatment with Ast IV was reversed by 2-MeOE2 treatment, which indicates that HIF-1α activation by Ast IV may result in the activation of iNOS signaling and confer protection against myocardial IRI." (PMID 25238237, 2014). "However, whether HIF-1α plays an important role in the cardioprotection of post-ischemia treatment with Ast IV requires further investigation." (PMID 25238237, 2014). "The protective role of HIF-1α is injury-severity dependent: mild ischemia promotes NRF2 nuclear translocation and enhances antioxidant responses, whereas severe ischemia suppresses NRF2 and exacerbates damage." (PMID 41602837, 2026). "Studies have demonstrated that activation of the HIF‐1α‐VEGFA‐Notch1 signaling pathway promotes angiogenesis within the cerebral microvascular system, thereby protecting against ischemia–reperfusion injury in the brain." (PMID 40019048, 2025). "Importantly, further in vivo analyses suggest that paeoniflorin may protect against retinal ischemia by downregulating ischemia-related upstream β-catenin and downstream HIF-1α, VEGF, and Ang-2, with similar effects to Wnt/β-catenin inhibitor DKK1, anti-angiogenic PEDF, and anti-VEGF Avastin." (PMID 41303406, 2025). "For a proangiogenic effect, Müller cells can produce HIF-1α and VEGF leading to ischemia-induced retinal neovascularization and vascular leakage." (PMID 39294742, 2024). "HIF-1α is a crucial transcription factor in the cardiovascular system, as it regulates gene expression of the CXCL12/CXCR4/ACKR3 axis during ischemia." (PMID 38994928, 2024). "Inhibition of HIF-1α with its inhibitor YC-1 can significantly decrease VEGF upregulation in neurons and reduce ischemia-induced BBB damage during acute cerebral ischemia." (PMID 35656098, 2022). "Mitochondrial dysfunction was reported to decrease HIF-1α signalling in hypoxia, and inhibiting activation of HIF-1α prevents mitochondrial dysfunction in hepatic ischemia-reperfusion (I/R) injury." (PMID 35396503, 2022). "To identify the therapeutic potential of these pathways, we investigated the activation of autophagy and of the central adaptation mechanisms (HIF1α, AMPK, NRF2) during the course of ischemia and reperfusion to obtain a timeline of their activation." (PMID 36157182, 2022). "HIF-1α and its downstream proangiogenic molecules such as VEGF-A play important roles in ischemia/hypoxia-induced angiogenesis." (PMID 35531958, 2022). "HIF-1α and HIF-2α can partially compensate for each other, although specific target genes are differentially regulated after ischemia." (PMID 34439764, 2021).
ischemia (continued). "Hypoxic preconditioning for 180 or 300 min can lead to the production of reactive oxygen species (ROS) and induce the production threshold of HIF-1α and EPO under ischemia, thus having a neuroprotective role through the NF-κ B/JAK2-tgf5 pathway." (PMID 34966392, 2021). "Previous studies showed that ACh upregulates HIF-1α, induces the expression of VEGF, and promotes angiogenesis to ameliorate the destructive effects of ischemia and hypoxia on cardiomyocytes." (PMID 35126151, 2021). "Another protein upregulated by HIF-1α is CXCR4, a chemokine receptor for SDF-1α also known as CXCL12, whose expression occurs in hypoxic tumoral microenvironment conditions and vascular ischemia." (PMID 32599834, 2020). "The altered proteins, including HSP72, HIF-1α, HO-1, MMP-9, and other ischemia-related mediators, are involved in significant biological functions associated with HIF-1α." (PMID 33162790, 2020). "Although the present study did not determine this relation, as the first step, we intended to assess the expression of HIF-1α and BDNF/TrkB/CREB proteins following ischemia/reperfusion injury." (PMID 32670026, 2020). "For instance, HIF-1α regulation of aquaporin-4 (AQP-4) and matrix metalloproteinase-9 (MMP-9) lead to edema and blood brain barrier (BBB) disruption during ischemia." (PMID 29045486, 2017). "Postischemia administration of 2.7 g/Kg/day XFZYD also significantly (I/R + XFZYD2.7: VEGF = 2.91 ± 1.59, p = 0.029; HIF-1α = 1.57 ± 0.61, p = 0.006; PKM2 = 2.62 ± 0.49, p = 0.002; RBP2 = 1.42 ± 0.52, p = 0.005) attenuated this ischemia-induced increase." (PMID 28709426, 2017). "Postischemia administration of 2.7 g/Kg/day XFZYD also significantly [I/R + XFZYD2.7 (VEGF = 1.90 ± 0.34; HIF-1α = 1.87 ± 0.22; PKM2 = 5.86 ± 0.95, p < 0.001; RBP2 = 5.19 ± 1.17, p = 0.008)] mitigated this ischemia-induced increase." (PMID 28709426, 2017). "In this pilot study, we investigated the feasibility of measuring acute HIF-1α and TLR4 expression in the peripheral circulation of pigs subjected to unilateral, ischemia-induced renal injury." (PMID 27149666, 2016). "In contrast to the renoprotective role of HIF-1α, increased TLR4 expression in response to ischemia further amplifies the initial damage via activation of inflammatory mediators." (PMID 27149666, 2016). "Stroke or ischemia gives rise to hypoxic conditions known to increase the incidence of AD and hypoxia increases transcription of BACE via overexpression of HIF-1α." (PMID 26228060, 2015). "CoCl2 treatment causes hypoxia, a key event during IRI, to alter gene and protein expression similarly to ischemia, which induces hypoxia by blocking the degradation of HIF-1α and enhancing subsequent HIF-1α accumulation." (PMID 23418539, 2013). "We further examined the expression of HIF-1α, TNF-α and IL1-β after ischemia and when treated with Melissa in the ischemic rat brain." (PMID 23351182, 2012). "HIF-1α mRNA expression was significantly lower in groups subjected to IPC or combined IPC and IPO when compared to the ischemia/reperfusion group (p = 0.002)." (PMID 21771288, 2011). "Hypoxia inducible factor- 1 alpha (HIF-1α), creatine phospho kinase-MB and reactive oxygen species in animal tissues and cells were measured to confirm ischemia in chick embryo." (PMID 20479865, 2010). "The external field reconstructs the bioelectric landscape, inducing oriented migration and proliferation of keratinocytes, fibroblasts, and endothelial cells, while up-regulating factors such as HIF-1α and VEGF to relieve local ischemia and promote neovascularization." (PMID 41574114, 2025). "On one hand, UQCRB enhances angiogenesis through mROS-mediated HIF-1α signal transduction and VEGF expression, a process with dual effects post-ischemia (potentially beneficial for revascularization but detrimental if excessive, contributing to cerebral edema)." (PMID 41305834, 2025).